Y_RNA (Y RNA )
Gene: Miscellaneous RNA gene on chromosome 1 (64,066,640 to 64,066,741, reverse strand). Ensembl gene ENSG00000200508.
Homologues: Orthologues: chimpanzee Y_RNA (99% identical), macaque Y_RNA (96% identical). Paralogues in human: RNY3 (87% identical), Y_RNA (86% identical), Y_RNA (85% identical), RNY3P1 (84% identical), Y_RNA (84% identical), Y_RNA (83% identical), RNY3P14 (82% identical), Y_RNA (82% identical), RNY3P12 (81% identical), RNY3P16 (81% identical), Y_RNA (81% identical), RNY3P11 (80% identical), and 92 more.